Y_RNA (Y RNA )
Gene: Miscellaneous RNA gene on chromosome 7 (76,523,605 to 76,523,706, forward strand). Ensembl gene ENSG00000238560.
Homologues: Orthologues: chimpanzee Y_RNA (99% identical), pig Y_RNA (73% identical). Paralogues in human: Y_RNA (100% identical), Y_RNA (99% identical), Y_RNA (93% identical), Y_RNA (90% identical), RNY3 (89% identical), RNY3P1 (88% identical), Y_RNA (87% identical), Y_RNA (86% identical), Y_RNA (85% identical), Y_RNA (84% identical), RNY3P13 (83% identical), RNY3P14 (83% identical), and 98 more.